INS (insulin)
Diseases named in the same sentence as INS in open-access papers (continued):
Sharing a sentence is not in itself a finding about the gene and the disease.
Hyperglycemia (continued). "Fasting hyperglycaemia represents an impairment in insulin secretion, while post-load hyperglycaemia represents a defect in insulin sensitivity." (PMID 40779219, 2025). "Maturation of these hiPSC-CMs is particularly important for producing models of diseases such as TTNtv-DCM, which typically occurs in older patients, and diabetic cardiomyopathy (DbCM), which is characterized by hyperglycemia and insulin resistance." (PMID 41180839, 2025). "Management strategies in our patient included aggressive control of hyperglycemia, with insulin therapy as the mainstay." (PMID 39171042, 2024). "In animals, in contrast to some of the studies in human subjects, a recent report indicated that VNS in adult mice exposed to endotoxin reduced inflammation-induced hyperglycemia by inducing insulin." (PMID 38248469, 2024). "In humans with CHF, hyperglycemia (defined as 144–180 mg/dL) is common due to impaired insulin mediated glucose uptake and cytokine mediated suppression of insulin release and has been shown to be a negative prognostic indicator." (PMID 39698307, 2024). "Our study revealed that ANX co-supplementation with insulin averts oxidative stress and inflammatory processes induced by hyperglycaemia." (PMID 39103403, 2024). "Poor R wave progression can also be attributed to diabetic cardiomyopathy, as the patient presented with hyperglycemia and was treated with insulin infusion." (PMID 39290925, 2024). "Hyperthyroidism accelerates the catabolism of the insulin hormone, precipitating hyperglycemia and consequently deteriorates the levels of glycemic control." (PMID 39845452, 2024). "GLP-1 receptors are functionally expressed in insulin-releasing neuroglia form cells in the rat cerebral cortex, and hyperglycemia significantly increases GLP-1 receptor expression." (PMID 39501255, 2024). "They worried about the effects of hyperglycemia on their baby’s health and size and work to manage the high glucose through adjusting their insulin, improving carbohydrate counting, and testing." (PMID 38570742, 2024). "Kcnk16 L114P mice show a similar phenotype, with neonatal islets showing a complete loss of glucose-stimulated [Ca2+]c influx, a drastic reduction in glucose-stimulated insulin secretion, and severe hyperglycemia by P4." (PMID 38700926, 2024). "Studies have shown that METS-IR is negatively correlated with insulin sensitivity, and higher METS-IR levels are associated with impaired β-cell function, further exacerbating hyperglycemia." (PMID 39514584, 2024). "Conversely, a 10-day treatment regimen of MaR1 administration in diet-induced obese mice reduced hyperglycemia, improved insulin sensitivity, and partially restored impaired insulin response in skeletal muscle." (PMID 39619489, 2024). "Safflower serotonin derivatives and other extracts can reduce fasting hyperglycemia by inhibiting intestinal α-glucosidase and improving insulin sensitivity." (PMID 39334757, 2024). "Maternal hyperglycemia due to decreased insulin sensitivity leads to high levels of blood glucose and hyperinsulinemia in a fetus." (PMID 38274586, 2024). "Age-related decreases in insulin sensitivity and glucose tolerance lead to impaired insulin signaling and hyperglycemia, which are potent inducers of oxidative stress and inflammation." (PMID 39584020, 2024). "In healthy humans, hepatic glucose uptake (HGU) during insulin stimulation increase, and defective stimulation of HGU by insulin predisposes to postprandial hyperglycemia due to defective liver glycogen storage." (PMID 38989003, 2024). "Correction of hyperglycemia by insulin therapy or a normal chow diet in HFD-fed obese control animals did not improve VAT senescence." (PMID 39063184, 2024). "Adults with hyperglycemia are characterized by peripheral IR consisting of impaired insulin action on peripheral tissues." (PMID 39057694, 2024).
Hyperglycemia (continued). "Hyperglycemia’s role in inducing ROS and inflammatory processes leads to insulin resistance, β-cell dysfunction, and, consequently, further hyperglycemia." (PMID 38892574, 2024). "The initial management of hyperglycemia can benefit from insulin sensitizers like metformin and thiazolidinediones (TZDs), which are oral hypoglycemic options." (PMID 39398333, 2024). "Long-acting medications such as liraglutide, semaglutide, dulaglutide, and exenatide long-acting release, comparatively, boost insulin secretion and decrease glucagon to control postprandial hyperglycemia." (PMID 39238749, 2024). "Consistent with pasireotide’s lower affinity for SSTR2 and higher affinity for SSTR5, hyperglycemia is attributed to reductions in insulin secretion with only mild inhibition of glucagon secretion." (PMID 38405148, 2024). "The increase in the plasma concentrations of insulin in stressed chickens were likely secondary to corticosterone-induced hyperglycemia." (PMID 38473137, 2024). "Administration of MSCs increased the level of insulin and reduced hyperglycemia in several studies employing animal models of T1D." (PMID 38892159, 2024). "Chronic hyperglycemia impairs GE and exacerbates gastroparesis symptoms, creating a reciprocal relationship wherein delayed GE further impairs calorie absorption and insulin release." (PMID 39664090, 2024). "Collectively, these changes result in insulin resistance, reduced glucose utilization, impaired insulin secretion, increased lipolysis, and protein catabolism, all of which can exacerbate hyperglycemia." (PMID 39458119, 2024). "It has been revealed that insulin therapy can significantly ameliorate hyperglycemia-induced DNA packaging defects." (PMID 38164482, 2024). "Previous studies have demonstrated that FXR agonists improve hyperglycemia and hyperlipidemia in diabetic mice by inhibiting liver gluconeogenesis and enhancing insulin sensitivity by increasing liver glycogen synthesis and glycogen content." (PMID 38774228, 2024). "The transplantation of the wild-type adipose tissue reversed hyperglycemia, considerably reduced (i.e., normalized) plasma insulin levels and hepatic steatosis, and increased muscle insulin sensitivity." (PMID 39769002, 2024). "Further research investigating GC and glucose dynamics within acute responses and accounting for other hormones (i.e. catecholamines, insulin and glucagon), are needed to understand the relative contribution of GCs to short- versus longer-term hyperglycemia." (PMID 38949462, 2024). "The primary outcome was blood glucose, and secondary outcomes included incidence of postoperative hyperglycemia, insulin level, blood urea, hunger, thirst, and anxiety." (PMID 38700117, 2024). "Of the two that required initiation of insulin, both had new referrals to endocrinology, and one had to stop treatment due to severe hyperglycemia and hospitalization." (PMID 38765324, 2024). "We have tested insulin secretion of the exposed cells stimulated by 2.5 mM glucose (hypoglycemia), 25 mM glucose (hyperglycemia), and 2.5 mM glucose in combination with 30 mM KCl, which stimulates insulin secretion independently on glucose intake." (PMID 39192017, 2024). "Nevertheless, many TNDM cases remained unsolved, probably because of a lesser “incentive” to pursue genetic testing in nonsyndromic patients with modest, remitting hyperglycemia treated with short-lived insulin therapy or only rehydration." (PMID 38408297, 2024). "Hyperglycemia impaired glucose homeostasis, resulting in substantial (P<0.05) elevated glucose and HbA1c levels and lowered insulin levels in diabetic rats." (PMID 38234664, 2024). "Of note, CGM use in people with T2DM on intensive multiple daily insulin regimens significantly reduced the number of all hospitalizations as well as hyperglycemia admissions within the Veterans Administration healthcare system." (PMID 38974988, 2024).
Hyperglycemia (continued). "Among mothers with GDM and information available on treatments (n=243), 24 (9.9%) mothers required the use of insulin in the management of hyperglycemia, the rest took dietary and life style interventions only." (PMID 39665025, 2024). "Automated glucose-responsive insulin delivery is a safe and effective strategy to minimize hyperglycemia in complex surgical populations." (PMID 39348314, 2024). "The exposure of L cells in the distal jejunum and proximal ileum to these nutrients also provokes the secretion of GLP-1 and other incretins, which amplify the hyperglycaemia-dependent secretion of insulin and the insulin-dependent disposal of glucose." (PMID 38451861, 2024). "In a vicious cycle, constant and progressive hyperglycemia exacerbates the malfunction of pancreatic β cells by intensifying ER stress, ultimately leading to insulin gene suppression." (PMID 39064493, 2024). "Hyperglycemia also downregulates insulin signaling in the brain by attenuating insulin receptor substrates and Akt signaling, leading to impairments in glucose metabolism and plasticity." (PMID 38505757, 2024). "As a rule, significant clinical symptoms of hyperglycemia prompt doctors to control glucose levels and consequently initiate treatment, often with insulin." (PMID 39407860, 2024). "By examining the third category, we gain an understanding that DM frequently presents with hyperglycemia, insulin abnormalities, metabolic irregularities, and various other symptoms." (PMID 39717099, 2024). "Certain anesthetic agents, such as volatile anesthetics, can reduce insulin secretion and contribute to intraoperative hyperglycemia." (PMID 39458119, 2024). "Hyperglycemia is often a result of either decreased insulin secretion from the pancreas, defects in the body's response to insulin, or a combination of the two." (PMID 39553396, 2024). "The received calls were for hypoglycemia, hyperglycemia, insulin dose adjustment, the learning of insulin techniques, information on insulin handling, oral medication inquiry, diet inquiry, timings of insulin, diabetic foot-related issues, etc." (PMID 39463462, 2024). "Hyperglycemia is a major contributor to oxidative stress, which further disrupts insulin secretion and stimulates the development of insulin resistance." (PMID 38234664, 2024). "At present, pancreatic β‐cells fail to produce enough insulin to make up for a chronic fuel surplus, resulting in eventual insulin resistance, hyperglycemia, and an excessive supply of glucose to the developing fetus." (PMID 38410499, 2024). "In a previous study, MSCs or their EVs, when administered to diabetic mice, significantly improve hyperglycemia, reduce glycosylated hemoglobin levels, increase insulin secretion, and improve hepatic glucose and lipid metabolism." (PMID 38343632, 2024). "Type 2 diabetes (T2D) is a metabolic condition characterized by hyperglycemia resulting from a combination of insufficient insulin secretion and resistance to insulin action." (PMID 38431555, 2024). "They disrupt the insulin signaling pathway in muscle, liver, and adipose tissues, resulting in hyperglycemia." (PMID 39203828, 2024). "Several factors contribute to postprandial hyperglycemia including impaired insulin secretion, insulin resistance, increased hepatic glucose production, and incretin dysfunction." (PMID 39768789, 2024). "Chronic hyperglycemia through multiple mechanisms have deleterious consequences on insulin secretion/synthesis in addition to insulin sensitivity." (PMID 38628217, 2024). "These metabolic alterations lead to peripheral insulin, which prevents glucose from entering cells, and so enhances hyperglycemia." (PMID 39683535, 2024). "Early postprandial hyperglycemia also allows for the release of insulin molecules that are partly bound to circulating insulin-IAA complexes and partly unbound and free to act." (PMID 39347250, 2024).
Hyperglycemia (continued). "Based on our findings that hyperglycemia potentiated ucOC-induced insulin secretion, we performed experiments with increasing ucOC concentrations (100–1000 nM) under 450 mg/dL glucose conditions." (PMID 39125265, 2024). "This condition results from the body’s ineffective utilization of insulin, leading not only to hyperglycemia but also to significant disruptions in lipid metabolism." (PMID 39770517, 2024). "Type 1 diabetes (T1D) is an autoimmune disease that affects the pancreatic β-cells that produce insulin, resulting in insulin insufficiency and hyperglycemia." (PMID 39273299, 2024). "Type 1 diabetes (T1D) is characterized by lymphocyte infiltration into the pancreatic islets of Langerhans, leading to the destruction of insulin-producing beta cells and uncontrolled hyperglycemia." (PMID 38490439, 2024). "This fatty acid did not only reduce the utilization of insulin-stimulated muscle glucose, exacerbating hyperglycemia, but also lead to lipotoxicity." (PMID 39086906, 2024). "This sharp rise necessitates a corresponding increase in insulin secretion to facilitate glucose uptake by tissues and to prevent hyperglycemia." (PMID 39766270, 2024). "One of the early changes with the onset of type 2 diabetes is a decrease in first-phase insulin release leading to postprandial hyperglycaemia." (PMID 38370356, 2024). "Single-node PAM inhibitors can induce significant increases in hyperglycemia and insulin secretion, which leads to the reactivation of the PAM pathway in patients and a reduction in single-node drug efficacy." (PMID 39456616, 2024). "Autoimmune destruction of pancreatic β-cells, which synthesize and release insulin, is associated with T1DM, causing hyperglycemia through insulinopenia." (PMID 38392069, 2024). "Nevertheless, few studies have reported that NF-κβ/TLR-4 and SERCA/Ca2+ pathways lower pancreatic β cell proliferation/insulin secretion in response to hyperglycemia." (PMID 38778421, 2024). "Despite matching, infants of mothers with poorly controlled GDM had a higher body mass and a higher weight-for-length percentile, probably resulting from enhanced secretion of insulin by the fetal pancreas in response to hyperglycemia." (PMID 39683537, 2024). "At the same time, insulin co-treatment preserved testicular tissue and spermatogenesis from the deleterious hyperglycemia-induced effects of oxidative stress on germ cells leading to higher sperm production and sperm motility." (PMID 38164482, 2024). "PLX-5622 treatment depleted hypothalamic microglia by >95% across animals, without body weight gain or food intake modification and prevented both the 3d HFD insulin hypersecretion and post-absorptive hyperglycemia." (PMID 37066282, 2024). "A time advantage of 15 min or especially 30 min opens a window of opportunity to prevent an episode of hypoglycemia or hyperglycemia by ingesting carbohydrates, changing the insulin delivery rate, or giving a correction bolus." (PMID 39518393, 2024). "Stress hyperglycemia can be driven by multiple factors, including hormone release (such as cortisol and adrenaline) and increased insulin resistance." (PMID 39172286, 2024). "This insulin resistance heightens lipolysis and elevates circulating free fatty acids, exacerbating hyperglycemia, especially during the cytokine storm phase." (PMID 39338165, 2024). "Hypertriglyceridemia and hyperglycemia are closely linked to hyperinsulinemia, and directly increase CRC risk by promoting fecal secondary bile acid secretion, altering insulin levels, and signaling pathways." (PMID 39103728, 2024). "Within the first 2 h after a high-GI/GL meal, hyperglycemia and hyperinsulinemia stimulate the uptake of nutrients through insulin-responsive tissues, glycogenesis and lipogenesis." (PMID 38794721, 2024). "Overall, hyperglycemia and increased insulin levels induced by HFD in GDM mice were alleviated by Cys supplementation." (PMID 38429982, 2024).
Hyperglycemia (continued). "The mechanism of the STZ-induced diabetic state includes its selective cytotoxicity to β-cells, which makes cells less active, leading to poor insulin sensitivity to glucose uptake by tissues and hyperglycemia." (PMID 39000039, 2024). "The most common therapeutic strategies were and still are exogenous insulin injection and oral hypoglycemics, which only manage hyperglycemia temporarily but cannot cure diabetic complications." (PMID 38666865, 2024). "The effects of chronic hyperglycemia on in vivo insulin secretion were examined after rats underwent 90% pancreatectomy, leaving intact the 10% of the pancreas between the common bile duct and the duodenal sweep." (PMID 38426504, 2024). "Poor insulin signalling reaction was once demonstrated in soleus muscle of 21-day-old weanlings exposed as foetus to hyperglycaemia, which means soleus can be first victim of elevated glucose exposure." (PMID 39043630, 2024). "Upon activation of the neurohormonal response, hepatic output of glucose increases via excessive gluconeogenesis, and insulin resistance can also be induced to exacerbate hyperglycemia." (PMID 38664806, 2024). "This trend is consistent with previous findings that dietary fiber-rich meals, compared with meals consisting solely of white rice, can increase GLP-1 levels, suppress postprandial hyperglycemia, and reduce the excessive secretion of endogenous insulin." (PMID 39599684, 2024). "Some individuals reported hybrid CLS to be more cautious than they expected when responding to hyperglycemia, resulting in frustration and a perceived need for manual insulin correction boluses." (PMID 39390689, 2024). "In general, symptoms of hyperglycemia and hypoglycemia can be corrected by discontinuing insulin or switching to a different type of insulin within a span of three to six months." (PMID 39575003, 2024). "Intake of sucrose fatty acid esters and CMC resulted in an adverse effect on obesogenic and metabolic biomarkers and induced hyperglycemia and hyperinsulinemia by increasing weight gain, fasting serum glucose and serum insulin levels, and HOMA-IR index." (PMID 38902371, 2024). "The patient demonstrated hyperglycemia on admission, hence started on variable rate insulin, and further investigations had been done to screen for metabolic syndrome." (PMID 39712682, 2024). "Although rare, rapid overcorrection of hyperglycemia with fluids and insulin can lead to CE, seizures, and death." (PMID 39360087, 2024). "Insulin therapy is effective in treating or preventing hyperglycemia in preterm infants, but it can lead to an increase in the incidence of hypoglycemia." (PMID 39339781, 2024). "Mutations and deficiencies in the CIII subunit are associated with sporadic myopathy, exercise intolerance, recurrent metabolic crisis, insulin-responsive hyperglycemia, and lactic acidosis." (PMID 38200189, 2024). "In support of this, we have shown that acute olanzapine treatment increases circulating glucagon, whereas protection against olanzapine-induced hyperglycemia is often paralleled by reductions in glucagon and/or the glucagon:insulin ratio." (PMID 38188526, 2024). "This decreased variability has been historically reported in patients on insulin pumps, and intuitively makes sense if using a hybrid-closed loop algorithm that acts to mitigate both hypo- and hyperglycemia." (PMID 39353188, 2024). "Local insulin secretion in intra-islets plays a critical role in suppressing glucagon secretion during hyperglycemia." (PMID 39149119, 2024). "hsa-MIR-6236 expression negatively correlates with hyperglycemia and glucose intolerance, and positively correlates with insulin sensitivity." (PMID 38918428, 2024). "Dysregulations of the pathways that control insulin secretion or insulin action frequently leads to development of hyperglycemia." (PMID 39507247, 2024). "Hyperglycemia up to 29.6 mmol/L was detected within the first week of her life, and insulin therapy (regular insulin and detemir) was initiated." (PMID 39596087, 2024).